ENSG00000207419
Synonyms: LOC124900221
Gene: Small nucleolar RNA gene on chromosome 6 (11,709,819 to 11,709,960, forward strand). Ensembl gene ENSG00000207419.
Gene Ontology:
Biological process: RNA processing
Cellular component: nucleolus
Homologues: Paralogues in human: SNORA67 (80% identical).